SCARNA9 (small Cajal body-specific RNA 9)
Synonyms: mgU2-19/30; Z32; lncC11orf54-1
Gene: Long non-coding RNA gene on chromosome 11 (93,721,513 to 93,721,865, forward strand). Ensembl gene ENSG00000254911.
Gene Ontology:
Biological process: RNA processing
Cellular component: nucleolus
Diseases named in the same sentence as SCARNA9 in open-access papers:
SCARNA9 is named in the same sentence as 3 diseases in open-access papers, as found by Europe PMC text mining. Sharing a sentence is not in itself a finding about the gene and the disease. The quoted sentences say what the papers report.
tumor (1 paper, 2023). "Small Cajal body-specific RNA 9 (SCARNA9) is an immune-related long non-coding RNA that influenced the development and progression of many tumors by regulating the immune components of the tumor microenvironment." (PMID 37974210, 2023).
SCARNA9 also shares sentences with these, for which no sentence is quoted: bacterial meningitis (1 paper); E. coli infection (1).